VEGFA (vascular endothelial growth factor A)
Diseases named in the same sentence as VEGFA in open-access papers (continued):
Sharing a sentence is not in itself a finding about the gene and the disease.
tumor (continued). "Tumor-specific genetic alterations and vascularization are linked to recurrence and prognostication (many germline vascular endothelial growth factor-A single nucleotide polymorphisms)." (PMID 37266003, 2023). "This causes tumour extravasation of the peptide and of co-administered payloads by a transendothelial endocytic mechanism that resembles vascular endothelial growth factor-A (VEGF-A)-induced transport vesicles called vesiculo-vacuolar organelles." (PMID 36982773, 2023). "Other TME-associated cells, such as T-regulated cells, dendritic cells, and tumor-associated adipose cells, also secrete pro-angiogenic factors, such as VEGFA, MMP9, IL10, TGF-β, and leptin, and consequently promote cancer angiogenesis." (PMID 36647777, 2023). "Our data also showed that increased levels of MMP7 were associated with VEGFA and were associated with tumor progression, metastasis, and immune invasion." (PMID 36672201, 2023). "The upregulation of VEGFA can induce angiogenesis and recruit monocytes to the tumor niche, which are then transformed into tumor-associated macrophages (TAM) in the tumor to participate in tumorigenesis." (PMID 37189418, 2023). "The other network included products of genes associated with tumour growth and cell proliferation (FN1, VEGFA), tumour progression and metastasis (CD44, ITGA2) and immune inhibition (NT5E)." (PMID 36649303, 2023). "Transcriptome-wide mutation analyses identify many cell-type-specific mutations including VEGFA mutations in tumor cells and HLA-A mutations in immune cells, highlighting the critical roles of different mutant populations in tumors." (PMID 37433798, 2023). "The CAF-like clusters involved multiple molecular mechanisms associated with tumor progression, angiogenesis via vascular endothelial growth factor A (VEGFA) production, and coordination of immune function through chemokine and cytokine production." (PMID 38328306, 2023). "Further, cancer‐associated fibroblasts (CAFs) directly facilitate tumor angiogenesis via pro‐angiogenic factors and produce VEGFA." (PMID 35832030, 2023). "VEGFA gene amplification is a high risk for OS patients with poorer tumor-free survival and its expression is associated with a higher risk of metastasis." (PMID 37749554, 2023). "Some scholars have found that expression level of VEGFA in the blood vessels and cells of a variety of tumors increase exponentially, and the expression status of VEGFA is significantly associated with the disease progression and prognosis of tumor patients." (PMID 35668376, 2022). "Analysis of differentially expressed genes revealed several differentially expressed genes in the HK-II high expressors associated with tumor progression (for example, VEGFA, CXCL8, and S100A being up-regulated)." (PMID 35677429, 2022). "They showed that Ang-2 and VEGFA blockade by a bispecific antibody (A2V) caused vascular regression, tumor necrosis along with improved antigen presentation by intratumoral phagocytes." (PMID 35392964, 2022). "FOXK2 was upregulated in ATC tissues, and the expression of FOXK2 was associated with tumor size, it promoted angiogenesis by inducing the transcription of VEGFA." (PMID 36172141, 2022). "For example, linc00665 can directly interact with the YB-1 protein and accumulate in the nucleaus, thereby increasing ANGPT4, ANGPTL3, and VEGFA expression and promoting tumor-associated angiogenesis in lung cancer." (PMID 35918758, 2022). "Modulation of VEGFA expression by ID4 protein in BC cells is also responsible for the reprogramming of tumor-associated macrophages (TAMs)." (PMID 35710947, 2022). "Particularly, VEGFA is overexpressed in many known tumors, including BCa, and its expression has been associated with tumor stage and progression as well as the patient’s prognosis." (PMID 35884419, 2022). "In cancer, VEGFA mainly comes from endothelial cells, hypoxic tumor cells and tumor-associated macrophages." (PMID 35203290, 2022).
tumor (continued). "The tumor vasculature commonly exhibits a number of vascular abnormalities with functional consequences resulting from chronic hypoxia and vascular endothelial growth factor-A (VEGFA) overproduction, causing protracted angiogenic stimulation." (PMID 35216427, 2022). "CXCR-4 (C-X-C chemokine receptor type 4), also known as fusin or CD184, like VEGFA, is closely associated with tumor formation and angiogenesis in different cancers." (PMID 34298612, 2021). "High VEGFA levels in GBM are associated with increased tumor aggressiveness and poor survival rates." (PMID 33718179, 2021). "VEGFA, vascular endothelial growth factor A is a key regulator of inflammatory and tumor-associated angiogenesis." (PMID 33865425, 2021). "Elevated expression of VEGFA by TAMs is associated with increased blood vessel permeability and attraction of migratory tumor cells." (PMID 34572013, 2021). "Exosomes delivering miR-497 in A549 cells suppressed tumor growth and inhibited the expression of several associated genes such as yes-associated protein 1, hepatoma-derived growth factor, cyclin E1, and vascular endothelial growth factor-A (VEGF-A)." (PMID 34677212, 2021). "circPRRC2A also caused an elevation in the expression of VEGFA, and the mechanism by which it functioned was through the sponging of miR-514a-5p and miR-6776-5p, both of which played tumor-suppressive roles." (PMID 34162394, 2021). "VEGFA is a considerable target for anti-tumor therapy, and its expression is negatively associated with the differentiation and prognosis of lung cancer." (PMID 34521875, 2021). "Previous study has indicated that the expression of VEGFA in tumor cells was positively associated with ANGPT2 and predicted poor survival." (PMID 31892982, 2020). "VEGFA gene encodes a well-studied pro-angiogenic factor that induces endothelial cell proliferation, migration, survival, and therefore contributes to tumor angiogenesis." (PMID 32331433, 2020). "We have identified that overexpression of miR526b/miR655 in MCF7 cells enhances tumor-associated angiogenesis and lymphangiogenesis by the production of VEGFA and that miRNA cell secretion enhances tube formation in vascular endothelial cells." (PMID 32707933, 2020). "In agreement with this study, we also noticed similar tendencies of SEMA3B, SEMA3G, SEMA3D and VEGFA mRNA level associations with patient survival and tumor malignancy grade." (PMID 33036421, 2020). "Galectin-1 (Gal-1) induces tumor-associated HuVEC proliferation and migration, by enhancing VEGFA effects, and HuVEC adhesion." (PMID 32766254, 2020). "Overexpression of vascular angiogenic factors, such as vascular endothelial growth factor A (VEGFA), is associated with rapid growth in tumour cells." (PMID 33158116, 2020). "Recently, we demonstrated that ProEGCG not only downregulated vascular endothelial growth factors (VEGFs) but also inhibited tumor-associated macrophage (TAM)-secreted VEGFA in EC." (PMID 33023525, 2020). "Surrogate markers of angiogenic activity (microvessel density and vascular endothelial growth factor A (VEGF-A) expression) were found to be associated with tumor grade, metastasis, and prognosis." (PMID 31151317, 2019). "The presence of VEGFA-secreting NK cells is associated with a poor prognosis and depends on the type and stage of the tumor." (PMID 31531018, 2019). "Conditional deletion of VEGFA in tumor cells of established tumors caused regression by reducing both microvascular density and the proliferation and renewal of CSCs." (PMID 30678134, 2019). "Our data demonstrates that lymphangiogenesis is upregulated in tumor bearing Stat4 deficient mice, as marked by increased VegfA expression in the lymph node, leading to an immune suppressive microenvironment that favors tumor growth." (PMID 32010142, 2019). "The expression of vascular endothelial growth factor A, which is the target gene of miR-150-5p, was significantly associated with the tumor stage." (PMID 29518940, 2018).
tumor (continued). "Correlation analysis revealed that changes in VEGFA isoform fractions were stronger associated with clinically significant tumor characteristics than alterations in expression levels." (PMID 29888133, 2018). "It has been shown that ALK-positive patients have higher levels of vascular endothelial growth factor-A (VEGF-A) and tumor vessel formations compared to EGFR and KRAS mutated NSCLC." (PMID 29318404, 2018). "We also engineered these cells to secrete VEGFA using an adenovirus encoding mouse VEGFA, which drives a strong angiogenic response characterized by increased tumor microvascular density." (PMID 29872538, 2018). "Increase in VEGFA-165 and VEGFA-121 expression levels is associated with ascites and feeble tumor capsule indicating their progression-stimulating role consistent with previously reported data." (PMID 29888133, 2018). "In contrast, the reduction of VEGFA-189 fraction and the increase in VEGFA-121 fraction were associated with advanced tumor stages estimated using TNM or BCLC (Bruix, Reig & Sherman, 2016) systems." (PMID 29888133, 2018). "We found that VEGFA gene copy number amplification/polysomy was associated with reduced macrophages, PD-1-positive tumor infiltrating lymphocytes and PD-L1 stromal expression." (PMID 28403223, 2017). "VEGFA can induce the accumulation of tumor-associated macrophages, MDSCs, Tregs, and inhibit the migration of T lymphocytes to the tumor." (PMID 29285252, 2017). "Taken together, these results suggest that CRCs with VEGFA gene amplification or Chr6 polysomy are associated with reduced PD-1-positive tumor infiltrating lymphocytes and PD-L1 stromal expression." (PMID 28403223, 2017). "Our results suggest that VEGFA amplification or Chr6 polysomy is associated with an altered tumor immune microenvironment." (PMID 28403223, 2017). "Our data showed that short term sunitinib treatment is associated with more tumor hypoxia and increased expression of Snail, VEGFA, and Oct4." (PMID 29383148, 2017). "SEMA3B and SEMA3F have been implicated in mediating tumor-suppressing effects, whereas VEGFA has been shown to promote tumor cell proliferation and survival by binding to NRP127–33." (PMID 29018205, 2017). "High release of CCK was frequently associated with the development of intravascular tumor emboli, which was correlated with increased vascular endothelial growth factor-A (VEGF-A)." (PMID 26941789, 2016). "The overexpression of NF90 restored VEGFA expression and rescued the loss of tumor angiogenesis caused by miR-590-5p." (PMID 27735951, 2016). "In cancer, the loss of VEGFA-regulated leakage was manifested as reduced tumour oedema, improved responsiveness to chemotherapy and suppressed metastatic spread due to an arrest in tumour cell intravasation." (PMID 27005951, 2016). "For example, vascular endothelial growth factor-A (VEGF-A) is a pro-angiogenesis gene that is associated with tumor angiogenesis and tumor malignancy, and it also induces tumor proliferation, migration invasion and survival." (PMID 26894862, 2016). "The vascular endothelial growth factor A (VEGF-A) plays a central role in tumour associated angiogenesis and in the pathogenesis of malignant ascites." (PMID 26673788, 2015). "CLN3 has a copy number gain encompassing the VEGFA locus, found in 3% of the cases and linked to higher tumor grade and vascular invasion and being an aggressive subgroup." (PMID 24943349, 2014). "For example, the vascular endothelial growth factor receptor FLT1 was found linked with its ligand VEGFA, both over-expressed in tumor samples." (PMID 24597571, 2014). "We next tested the expression of VEGFA under DEXA treatment since VEGFA is associated with tumor angiogenesis, cell stress, hypoxia and brain edema." (PMID 24714627, 2014). "Wolf G. and co-workers suggested a potential role of this VEGFA polymorphism on the variability of FDG uptake in tumour tissue." (PMID 23631762, 2013).
tumor (continued). "Patterns of gene expression associated with the 2,656-tumor dataset were found in both TCGA datasets, including the low PC4a gene expression signature of high VEGFA and low SEMA3B, SEMA3C, SEMA3F, and PLXNB1." (PMID 23667446, 2013). "VEGFA is a crucial growth factor mediating tumor angiogenesis, and its expression has been associated with advanced grade, stage and recurrence of UCC." (PMID 22895562, 2012). "Deregulation of MYC, vascular endothelial growth factor A, and interleukin 6 has been reported to be strongly associated with tumor growth and metastatic invasion." (PMID 23049873, 2012). "Although a role for VEGFA in malignant progression was implicated, the exact mechanism by how increased VEGFA levels influence tumour growth is still not completely understood." (PMID 22045186, 2011). "VEGFA is known to be an angiogenic factor and is closely associated with tumor angiogenesis." (PMID 41425852, 2025). "Furthermore, in LUSC, m6A modification promotes the secretion of VEGFA and other cytokines by cancer-associated fibroblasts (CAFs), thereby remodeling the tumor microenvironment and enhancing angiogenesis and metastasis." (PMID 40740874, 2025). "Using deep spatial transcriptomics and single-nucleus RNA sequencing (snRNA-Seq), we identified the possible section of the primary tumour and cell population, respectively, which likely contributed to metastases development, and implicated VEGFA as a spatially informed marker." (PMID 41168392, 2025). "VEGFA correlated positively with M2 macrophages—a subtype linked to immunosuppressive activity—and negatively with T cells, further supporting its role in blunting anti-tumor immunity." (PMID 40943183, 2025). "Additionally, expression of VEGFA, a known angiogenesis factor, was also spatially variable, with the highest levels in the tumour periphery, potentially causing parts of the primary tumour to be more resistant to immune therapy." (PMID 41168392, 2025). "VEGFA is implicated in cancer angiogenesis, tumor development, and metastasis." (PMID 39457390, 2024). "Macrophages associated with high levels of genes associated with IFN and ROS were found in both the tumor and interface zones, whereas macrophages associated with VEGFA expression and a hypoxia‐associated gene expression signature were found only in the tumor zone." (PMID 38426622, 2024). "Based on the outgoing signal of VEGFA from fibroblasts to TECs and the causal relationship between VEGF and tumor angiogenesis, we investigated the expression levels of diverse genes associated with pro-angiogenic factors and the endothelial index between TECs and NECs in BRCA1 MT TNBC patients." (PMID 38182557, 2024). "Some studies have shown that VEGFA is related to tumor infectivity and tumor susceptibility." (PMID 37898675, 2023). "For instance, miR-374a is lower in the center of tumor mass compared to the edges and may be associated with differential and opposite expression of its angiogenic targets VEGFA and vascular cell adhesion molecule 1(VCAM1) in tumor mass." (PMID 37583933, 2023). "Mutations involving copy number alterations of the VEGFA gene could account for its overexpression in tumor tissue." (PMID 37893095, 2023). "HIF-2 selective or co-regulated target genes associated with tumor growth and metastasis (VEGFa, PAI1, MMP9, GLUT1) were induced in acetylation-intact (K3) HIF-2α and nuclear-localizable (WT) Acss2 knockdown/rescue cells under hypoxia and low glucose conditions." (PMID 36862715, 2023). "Moreover, HIF-1 also increases glycolysis and the release of lactate acid into the TME, and lactic acid induces tumor-associated macrophages to secrete more VEGFA." (PMID 36765912, 2023). "Similarly, VEGFA induces angiogenesis and higher levels of VEGFA are associated with tumor survival, growth, and metastasis." (PMID 37803875, 2023).
tumor (continued). "The increased expression of VEGFA and other pro-angiogenic factors in tumor cells in patients with GC is considered a negative prognostic factor and is associated with an immunosuppressive tumor microenvironment." (PMID 36874116, 2023). "Besides, several tumor-related genes, like VEGFA, TBX2, and TGFB1, were also enriched in the high-risk group." (PMID 36203430, 2022). "Moreover, CXCR2-positive MDSCs are attracted to metastatic sites by CXCL1 derived from tumor-associated macrophages (TAM) due to the stimulation of VEGFA released from primary tumor cells." (PMID 35911705, 2022). "Notably, among the genes that mutated the least is vascular endothelial growth factor (VEGFA), a molecule that plays an established role in tumor angiogenesis." (PMID 35619151, 2022). "The vascular endothelial growth factor A (VEGF) gene encodes an angiogenesis cytokine, which induces proliferation and migration of vascular endothelial cells, and the genetic variants of VEGF are correlated with tumor risk." (PMID 35860595, 2022). "Moreover, TGFβ also manages PC angiogenesis by enhancing the disparity of cancer-associated fibroblasts (CAFs), which subsequently promotes tumor angiogenesis via intensifying VEGFA development." (PMID 34576107, 2021). "M2 macrophages are considered activated tumour-associated macrophages and are known to produce inflammatory signals and express high levels of growth factors that stimulate angiogenesis and lymphangiogenesis, such as VEGFA and VEGFC." (PMID 33572413, 2021). "Also, VEGFA can act as a crucial regulator of the cancer-immune circulation via generating considerable modifications, inducing immune tolerance and causing tumor immune evasion." (PMID 34497663, 2021). "Interestingly, high expression of VEGFA in the primary tumor was positively associated with other ligands and receptors with regards to LNM, implying a mutual effect." (PMID 34836311, 2021). "In addition, VEGFA can influence physiology and tumor-induced angiogenesis, whereas elevated VEGFA gene expressions are associated with tumor progression, recurrence, and survival." (PMID 34497510, 2021). "Since the MESH1 was induced by extracellular nutrient (cystine) deprivation, we focused on genes that encoded proteins that modulate tumor angiogenesis and microenvironments, including vascular endothelial growth factor A (VEGFA) and Serpin Family E Member 1 (SERPINE1)." (PMID 34294679, 2021). "Our data suggest that upregulation of three angiogenesis‐associated genes including HIF‐1, EIF4E2 and VEGFA in TNBC could be mediated by circ_0047303 through sponging the tumour‐suppressive miRNAs." (PMID 34791795, 2021). "A basic molecule implicated in tumor angiogenesis is the vascular endothelial growth factor A (VEGF-A) which might have both angiogenic and anti-angiogenic effects depending on the splicing variants acting on tumor endothelial cells." (PMID 34356101, 2021). "VEGFA is found to be associated with tumor proliferation, migration and invasion." (PMID 33962397, 2021). "The results of meta-analysis were consistent with the protein abundance, that increased VEGFA mRNA level were significantly associated with advanced tumor stage (OR=1.93, 95% CI: 1.33-2.82, P=0.588, and I2=0.0%) and big tumor size (OR=1.70, 95% CI: 1.05-2.74, P=0.385, and I2=5.0%) in ADC patients." (PMID 31892982, 2020). "Moreover, it was demonstrated that β1-integrin was required for tumor cell VEGFA-mediated extravasation, which was associated with vascular remodeling." (PMID 33521055, 2020). "In tumor cells deficient for VEGFA, CAFs produce VEGFA to sustain angiogenic processes." (PMID 32775327, 2020). "Lower mRNA expression of SEMA3B, SEMA3D, SEMA3G, and PLXNA2 or higher mRNA expression of SEMA3F, NRP1, ITGB3, ITGA5, and VEGFA genes were detected in the older patient group and associated with the higher tumor grade, wild-type status of IDH, and lower rate of survival time (p < 0.05)." (PMID 33036421, 2020).